MIR1291 (microRNA 1291)
Synonyms: hsa-mir-1291; MIRN1291; mir-1291
Gene: MicroRNA gene on chromosome 12 (48,654,444 to 48,654,530, reverse strand). Ensembl gene ENSG00000281842.
Homologues: Orthologues: chimpanzee ptr-mir-1291 (100% identical).